ICAM1 (intercellular adhesion molecule 1)
Diseases named in the same sentence as ICAM1 in open-access papers (continued):
Sharing a sentence is not in itself a finding about the gene and the disease.
cancer (continued). "Although a role for IL-6 in metastasis has been implicated in some cancer cells, the signaling pathway for IL-6 in cell motility and ICAM-1 expression in human OSCC has not been extensively studied." (PMID 24398980, 2014). "In addition, it has been reported that Dicer-regulated microRNAs 222 and 339 promote resistance of cancer cells to cytotoxic T-lymphocytes by down-regulation of ICAM-1." (PMID 23696794, 2013). "Therefore, c-Jun activation is mediated by WISP-1–increased cancer metastasis and ICAM-1 expression." (PMID 24205072, 2013). "In addition, MUC1 specifically binds to ICAM-1 on the surface of endothelial cells, increasing the adhesion between heterogeneous cells and leading to invasion of the cancer cells into the vascular wall with subsequent metastasis." (PMID 23708102, 2013). "Finally, an E-selectin and SM3 combined surface coating captured approximately 30% of the total number of interacting cancer cells comparable to the number of adhered cells when utilizing E-selectin and ICAM-1 combined surfaces." (PMID 23805168, 2013). "Interestingly, ICAM1 has been validated as a target for miR-221 or miR-222 in cholangiocytes, epithelial and cancer cells." (PMID 22535415, 2012). "This indicates that ICAM-1 expression may be of functional importance in cancer cell adhesion and motility." (PMID 22028734, 2012). "However, in some primary and secondary cancer cells, the ICAM-1 expression is lower than in normal cells." (PMID 23300837, 2012). "The interaction between ICAM-1 and its specific ligand may facilitate adhesion of cancer cells to the vascular endothelium and subsequently in the promotion of metastasis." (PMID 23098564, 2012). "This study demonstrates that culture of CT26 cancer cells as multicellular spheroids leads to the expansion of a LFA-1-expressing cancer cell subpopulation able to further secrete VEGF in response to soluble ICAM-1, via COX-2-dependent mechanism in vitro." (PMID 18844982, 2008). "This study examines for the first time the serum concentrations of circulating VCAM-1 and E-selectin in a consecutive series of 110 cancer patients seen in a general medical oncology clinic, and confirms and extends previous studies reporting measurement of circulating ICAM-1." (PMID 7686390, 1993). "Additionally, direct cell–cell interactions between cancer cells and endothelial cells could activate signaling pathways that upregulate ICAM‐1." (PMID 40223399, 2025). "In addition, to unlock the potential of ADC for cancer therapy, we also sought to develop a strategy to enhance the efficacy of ICAM1‐ADC through combination with DAC, although the efficacy of ICAM1‐ADC as a single agent was remarkable across the preclinical models." (PMID 38874532, 2024). "Likewise, cancer biomarker (ICAM1) was downregulated in CF PDEs96,97." (PMID 39687022, 2024). "Thus, ICAM-1‒FGG inhibitor may function as a promising therapeutic co-target in combination with other targeted drugs in cancer therapy." (PMID 39168965, 2024). "ICAM1 expression pattern may vary in different types of cancer." (PMID 37671167, 2023). "However, cancer cell-intrinsic knockout of Icam1 reduces tumors responsiveness to immunotherapy." (PMID 36871040, 2023). "Therefore, the ICAM-1 acts as an anti-cancer-targeted molecule 9-12." (PMID 37575276, 2023). "In addition, ICAM-1 plays an important role in supporting cancer malignancy." (PMID 37575276, 2023). "ICAM-1 therefore might be a primary receptor for CVA11 entry into cancer cells." (PMID 37046036, 2023). "Thus, immune escape may be achieved by limiting the influx of immune effectors into cancer tissue through down-regulation of endothelial adhesion molecules ICAM-1 and VCAM-1." (PMID 35630004, 2022). "Finally, the adhesion molecule ICAM-1 is frequently downregulated by cancer cells which might prevent CD8 T cells to kill their targets." (PMID 36189315, 2022).
cancer (continued). "Because the reduction of Ikaros and EZH2 impact cancer cell growth and increase recognition of infected cells by the host immune system through increased ICAM-1 and B7-2, Pom may have both a direct and an indirect effect on the survival of HTLV-1-infected cells." (PMID 35602479, 2022). "Notably, CD276, PGFBI, ENTPDI, and ICAM1 were highly expressed in most of the human cancers." (PMID 36105106, 2022). "The common practice of cancer cell implantation involves a large number of cells that results in massive cell death and local inflammation that could mask any intrinsic or extrinsic effects resulting from ICAM-1 deletion." (PMID 35911772, 2022). "It would be interesting to investigate the molecular mechanism involved in this process, such as molecules involved in EC-cancer cell interaction, and it is important to note that the increase in ICAM1 expression in ECs observed in this study could be involved in this process." (PMID 36248978, 2022). "Notably, we show that DNMTis may remodel cancer cells’ immune cytoskeleton or upregulate general adhesion molecules such as ICAM-1." (PMID 33846331, 2021). "NMPs can also contribute to increased ICAM-1 expression in endothelial cells and increased reactive oxygen species production; all of which lead to increased systemic inflammation and may promote cancer progression." (PMID 34416874, 2021). "Moreover, neutrophils expressing β2 integrin may also enhance CTC-EC adhesion by interacting with ICAM1 expressed by cancer cells and ECs in breast cancer." (PMID 33498251, 2021). "The role of pycnogenol in inhibiting NFκB activation, and vascular cell adhesion molecule 1 (VCAM-1) and intercellular adhesion molecule 1 (ICAM-1) expression suggests that this antioxidant compound may play a role in cancer prevention and atherogenic processes." (PMID 34205739, 2021). "TIMP-3 downregulation is related to cancer invasion and metastasis in various cancers; however, higher serum level of TIMP-1 is associated with lower response to therapy in breast cancer patients, and TIMP-1 has been used as a biomarker along with MMP-2 and ICAM-1 for pancreatic cancer." (PMID 32466129, 2020). "Therefore, the role of ICAM-1 in efferocytosis makes it a promising target for cancer treatment." (PMID 32370748, 2020). "Thus, similarly to that reported for certain oncogenes (i.e., Myc and Ras), AF1q has been shown to be endowed with a dual function in malignancy, being a protein apparently involved in both initiation and promotion of cancer progression through regulation of ICAM-1 expression." (PMID 31297450, 2019). "Furthermore, we observed that both the mRNA and protein levels of a collection of NF‐κB downstream effectors that are central co‐ordinators of cancer cell metastasis, such as ICAM1, VCAM1 and MMP9, were decreased by RPS15A knockdown, but increased by RPS15A overexpression." (PMID 30661291, 2019). "Co-localization of AsPC-1 exosomal ICAM-1 with macrophage CD11c suggests that uptake of AsPC-1 exosomes occurs via protein-mediated exosome-docking at the macrophage cell surface, and ICAM-1 could also promote cancer cell exosome uptake by other CD11c+ immune cells in the TME or at metastatic sites." (PMID 30383833, 2018). "However, ICAM1 is hypothesized to facilitate the attachment of carcinoma cells to the lymphatic endothelium and therefore promote the micro-metastatic movement in regional lymph nodes." (PMID 30082828, 2018). "Neutrophil transmigration has also been demonstrated to be a factor influencing CTC extravasation and metastasis, as the CTCs might use the activated leukocytes as some sort of “facilitator” for their own transmigration by binding of cancer cell ICAM-1 to neutrophilic CD11b (integrin αM)." (PMID 29326939, 2017). "Thus, increased ICAM-1 stability might promote cancer progression and metastatic activity, making it a potential major regulatory mechanism in cancerous conditions." (PMID 29137327, 2017).
cancer (continued). "In addition, enhanced killing of celecoxib-treated cancer cells was reversed by preincubation of LAK cells with an antibody to lymphocyte function associated antigen 1 (LFA-1), suggesting intercellular ICAM-1/LFA-1 crosslink as crucial event within this process." (PMID 26513172, 2015). "Although it is currently unclear how the interaction of M2a macrophages with the carcinoma aggregates via integrin/ICAM-1 can promote aggregate dissociation, it is likely that this interaction may act in synergy with secreted factors such as TGFβ to enhance EMT." (PMID 26231039, 2015). "Therefore, c-Jun activation is mediated by IL-6-increased cancer metastasis and ICAM-1 expression." (PMID 24398980, 2014). "However, in the respective HUVECs containing cultures, blocking of VAP-1 or ICAM-1 did not cause any change in the adhesion of both cancer cells." (PMID 24900957, 2014). "Thus, the biological significance of ICAM-1 expression in cancer remains controversial." (PMID 24069166, 2013). "Because the intercellular adhesion molecule (ICAM)-1, has been shown to play an important role in the adhesion of cancer cells to endothelial cells and therefore in metastasis, we sought to examine whether OME affects the expression of this adhesion molecule in MDA-MB-231 cells." (PMID 23874773, 2013). "Therefore, we expected a reduction by expression of the Tcf/LEF transcription factor activated in cancer cells, as well as an increase in the expression of a variety of factors including cyclin D, c-myc, ICAM-1 and c-jun, which are involved in the promotion of cancer cell cycle and proliferation." (PMID 23982808, 2013). "In addition, ICAM-1 may be expressed by cancer cells themselves and contribute to their invasiveness." (PMID 23098564, 2012). "Therefore, upregulation of LFA-1 expression on cancer cells at this early stage of the hepatic metastasis process may contribute to VEGF production by metastatic cells interacting with liver-derived ICAM-1." (PMID 18844982, 2008). "These known NF-κB target genes, such as IL6, IL8, BIRC2 (clAP-1), ICAM1, YAP1, CDKN1A (p21), CSF2, CCDN1, IL1A, IL1B, and so on, include many that have been independently confirmed to be differentially expressed and pathologically implicated in HNSCC and other cancers." (PMID 18334025, 2008). "Consistently, the expression of CDKN1C and KIT was lower in cancers, including KIRC, KIRP, and BRCA, while ICAM1, SSX2IP, and TNFSF10 were higher in cancers, including STAD and CESC, opposing the effects of miR-221/222-3p." (PMID 41602427, 2026). "Key molecules for cancer progression were inhibited (IL6, IL4, CXCL8, CXCR4, CXCL12; ICAM1, CD44 and BCL2), and pro-apoptotic BAD was activated." (PMID 41595551, 2025). "HSP90AA1 aids antigen release from cancer cells in TIME, while EZH2, STAT1, and ICAM1 hinder immune cell infiltration." (PMID 40352921, 2025). "In this study, we developed a prediction model for the “inflammation-cancer transition” using six predictors: ARG2, HSP90AA1, EZH2, ICAM1, macrophage M1, and activated CD4 memory T cells." (PMID 40352921, 2025). "However, in contrast to these cancer cells, NF-κB activation may only be at the basal level in A549 cells because we previously showed that the expression of NF-κB-responsive target genes, such as ICAM-1, was negligible in unstimulated A549 cells." (PMID 41302385, 2025). "Immunostaining for ICAM1 in CD8+ T cell and cancer cell cocultures aligned with this observation, with ICAM1 being enriched but evenly distributed within the cell–cell contact site." (PMID 40445758, 2025). "We searched for other potential overlaps and found that CXCL2, LIF, UBE2C, KRT5, ICAM1, and CXCL8 were significantly upregulated in STIC lesions identified in patients with cancer compared with adjacent normal epithelium." (PMID 40689422, 2025). "We also validated the LC substrate candidates CLMP, ICAM1, PCDH17, as well as the cancer-related GPNMB and TIMD4 as substrates." (PMID 40593564, 2025).
cancer (continued). "TF, fVII, intercellular adhesion molecule-1 (ICAM-1), and multiple pro-inflammatory cytokines can be induced in response to hypoxia in EOC cancer cells at the gene expression level, leading to the autonomous production of the TF–fVII complex." (PMID 39149564, 2024). "We also found that high PD-L1, ICAM1, and CXCL10 levels all correlated with better immunotherapeutic efficacy in patients with all cancers." (PMID 38953994, 2024). "Mechanistically, BCL6 suppress pro-inflammatory cytokines expression by HCC cancer cells and promoted the expression of immune suppressive protein ESM1, which was reported to be antagonist of ICAM-1 in binding to T cell surface protein LFA-1." (PMID 38956432, 2024). "The surface of endothelial are covered with adhesion molecules, including ICAM-1 and VCAM-1, which mediate the adhesion and extravasation of cancer cells." (PMID 38230220, 2024). "ICAM-1 and VCAM-1 are cell adhesion molecules that play a crucial role in the binding of cancer cells to mesothelial cells." (PMID 38689325, 2024). "Taken together, our study demonstrates that FGG binds to ICAM-1 on NSCLC cell surface and triggers anti-apoptotic signaling in cancer cells, therefore protects cancer cell from apoptosis." (PMID 39168965, 2024). "Disruption of ICAM-1–FGG interaction suppresses anti-apoptotic signaling and consequently activates caspase-9/3 pathway, leading to cancer cell death." (PMID 39168965, 2024). "Of note, cluster C6 cancer cells mainly came from two patients (P8 and P9), in which more than 90% of cancer cells were demarcated with triple expression of CD24/CD47/ICAM1." (PMID 38169544, 2024). "Our data highlighted a significant enrichment of certain cellular adhesion molecules, including MCAM, EpCAM, ICAM-1, EGFR, and ALCAM, in cancer EVs relative to hTERT-immortalized MSC EVs." (PMID 38786083, 2024). "In this study, we found that TBMS1 treatment lowered VEC expression of cancer adhesion molecules (ICAM-1 and VCAM-1), and reduced cancer cells adhesion on VEC monolayers." (PMID 38230220, 2024). "Receptor-ligand interaction analysis revealed that the pleural metastatic niche was aggravated by cross-talk between mesothelial cells-cancer cells/immune cells via TNC and ICAM1." (PMID 37649596, 2023). "This heatmap, based on a dataset including samples from NILM, ASC-US, and ≥LSIL groups, displays two main clusters: cancer markers (MCM3, CEACAM5, S100P, ICAM1) on the left and healthy markers (CRNN, EVPL, DSC2) on the right side of the figure." (PMID 37445651, 2023). "In cancer cells, tumour necrosis factor-alpha (TNF-α) can stimulate the expression of intercellular adhesion molecule-1 (ICAM-1) through the activation of nuclear factor-kappa B (NF-κB)." (PMID 38098026, 2023). "Correlated with the level of ICAM‐1, 4T1 cancer cells were less lysed by CD8+ T cells than CT26 cancer cells, indicating that ICAM‐1 depletion in 4T1 rarely affects CD8+ T cell cytotoxicity." (PMID 37097643, 2023). "As a matter of fact, ICAM1 downregulation has been shown to decrease migration of the MCF7 cell line and its blockade has been reported to inhibit cancer cell migration in vitro." (PMID 37297006, 2023). "Collectively, expression of ICAM1 and ICAM-1 cleavage related metalloproteinases is elevated in various human cancers." (PMID 37732732, 2023). "We uncovered a Hippo regulon in neutrophils with unique YAP signature genes (e.g., ICAM1, CD14, EGR1) distinct from those identified in epithelial and/or cancer cells." (PMID 36921037, 2023). "Network analysis identified a key role of mesothelial cells, which communicated with cancer cells by TNC and LIF, and distinct immune cells, including all subtypes of DCs, macrophages, and monocytes by ICAM1." (PMID 37649596, 2023).
cancer (continued). "ICAM‐1 has a soluble isoform and a membrane‐bound form; therefore, we evaluated soluble ICAM‐1 (sICAM‐1) production in cancer cells." (PMID 37097643, 2023). "CD54, also known as Intracellular adhesion molecule 1 (ICAM1), or BB2, is a transmembrane glycoprotein of the immunoglobulin superfamily that is aberrantly overexpressed in several cancers, including myeloma." (PMID 37111346, 2023). "We first performed a quantitative and unbiased screening of cancer-related antigens using comparative flow cytometry in a panel of human CCA cell lines, and identified intercellular adhesion molecule-1 (ICAM1) as a therapeutic target for CCA." (PMID 37717087, 2023). "Researchers have reported that elevated intercellular adhesion molecule-1 (ICAM-1) expression in cancer cells and increased release of serum ICAM-1 from cancer cells are connected to cancer progression." (PMID 37047765, 2023). "To evaluate the expression of ICAM1 and ICAM-1 cleavage related proteases, we analyzed gene expression of 22 human cancers obtained from The Cancer Genome Atlas (TCGA) and Genotype-Tissue Expression Portal (GTEx)." (PMID 37732732, 2023). "ICAM1, E-selectin, VCAM1, neuronal cadherin (N-cadherin), and integrins are among the best characterized molecules of the ECs involved in cancer cell adhesion onto endothelium and cancer cell extravasation." (PMID 36248978, 2022). "PGE2 binds to PGE receptor (EP1) and activates protein kinase δ (protein kinase Cδ, PKCδ)/c-Src/AP-1 signaling pathway, upregulates intercellular adhesion molecule 1 (ICAM-1), and promotes the metastasis of cancer cells." (PMID 36246294, 2022). "Some ligand‒receptor pairs were significantly enriched between cancer cells and T cells, such as the TNF family and ICAM1." (PMID 36127333, 2022). "Cancer cells can also provide co-stimulation, e.g., by CD80 and intercellular adhesion molecule 1 (ICAM-1) that bind to CD28 and lymphocyte function-associated antigen 1 (LFA-1) on T cells, respectively." (PMID 36230402, 2022). "It negatively affects cancer immune modulation via TGF-β activation and intercellular adhesion molecule-1 shedding (ICAM-1)." (PMID 35745729, 2022). "This section discusses six shedding examples that influence cancer progression, namely, CD44, ICAM-1, DDRs, syndecans, EphA2, and HB-EGF." (PMID 36132127, 2022). "Intercellular adhesion molecule 1 (ICAM1) is a transmembrane protein that participates in direct interactions between cells, including cancer cell and vascular endothelial cell." (PMID 36523635, 2022). "In fact, the coincubation of ICAM1-CAR-T cells with TNBC cells presented the specific and robust killing of cancer cells." (PMID 35414783, 2022). "The research showed that ICAM1 was not only a key promoter of the aggregation of homotypic CTC clusters, but also drove heterotypic adhesions between cancer cells and endothelial cells." (PMID 36059616, 2022). "Intercellular adhesion molecule-1 (ICAM-1) is a 90-kDa cell surface glycoprotein of the immunoglobulin superfamily, which has been shown to be responsible for cancer metastasis." (PMID 36016615, 2022). "To explore the biological function of ICAM-1 in CRC, we first screened its correlation with cancer hallmarks using the GSEA database." (PMID 35487888, 2022). "For instance, butyrate decreased intercellular adhesion molecule 1 (ICAM1) expression in the oral squamous carcinoma cell line HSC2 and promoted the migration and invasion of carcinoma cells." (PMID 36232340, 2022). "While our research focused on elucidating the role of ICAM1 in lung metastasis of TNBC, its functional significance in the lung metastasis of other cancer types needs to be further investigated." (PMID 34381029, 2021). "ICAM1, MMP1, and MMP3 are the well-known biomarkers participating in regulating cancer cell migration and invasion." (PMID 34544905, 2021).